CDHR1 (cadherin related family member 1)
Description:
Potential calcium-dependent cell-adhesion protein. May be required for the structural integrity of the outer segment (OS) of photoreceptor cells (By similarity).
Synonyms: prCAD; KIAA1775; PCDH21; CORD15; RP65
Tractability: Antibody: UniProt places it where antibodies can reach, with medium confidence; UniProt predicts a signal peptide or a membrane-spanning region; its Gene Ontology location is reachable by antibodies, with medium confidence.
Gene: Protein-coding gene on chromosome 10 (84,194,537 to 84,219,621, forward strand). Ensembl gene ENSG00000148600.
Subcellular location: Cell membrane
Subcellular location (Human Protein Atlas): Golgi apparatus
Gene Ontology:
Molecular function: cell adhesion molecule binding; calcium ion binding
Biological process: photoreceptor cell maintenance; photoreceptor cell morphogenesis; photoreceptor cell outer segment organization; cell adhesion; cell-cell adhesion; homophilic cell-cell adhesion
Cellular component: plasma membrane; membrane; photoreceptor outer segment membrane
Genetic constraint (gnomAD): Loss-of-function variants: 59 observed, 72.98 expected, observed/expected ratio (o/e) 0.81, 90% interval 0.65 to 1. The upper end of that interval is the gene's LOEUF score, 1, which puts it in group 4 of 6, group 1 being the genes least tolerant of losing a copy. Missense variants: 1,176 observed, 1,136 expected, observed/expected ratio (o/e) 1.04, 90% interval 0.99 to 1.09. Synonymous variants: 465 observed, 456.06 expected, observed/expected ratio (o/e) 1.02, 90% interval 0.94 to 1.1.
Gene-disease validity (ClinGen):
ClinGen rates the evidence that CDHR1 causes each of these diseases.
retinitis pigmentosa 65 (autosomal recessive): Definitive.
Homologues: Orthologues: chimpanzee CDHR1 (99% identical), macaque CDHR1 (98% identical), mouse Cdhr1 (85% identical), rat Cdhr1 (85% identical), guinea pig CDHR1 (85% identical), rabbit CDHR1 (85% identical), dog CDHR1 (83% identical), pig CDHR1 (83% identical), tropical clawed frog cdhr1 (64% identical), zebrafish cdhr1a (57% identical), zebrafish CDHR1 (48% identical). Paralogues in human: CDHR2 (27% identical), CDH23 (24% identical), DCHS1 (23% identical), DCHS2 (22% identical), PCDH11X (22% identical), PCDH9 (21% identical), PCDH1 (21% identical), PCDH7 (21% identical), PCDH11Y (21% identical), CDH2 (20% identical), PCDH20 (20% identical), CDH1 (19% identical), and 21 more.